MRPS30-DT (MRPS30 divergent transcript)
Synonyms: BRCAT54; BRCAT107; LINC02224
Gene: Long non-coding RNA gene on chromosome 5 (44,495,094 to 44,809,850, reverse strand). Ensembl gene ENSG00000251141.
Diseases named in the same sentence as MRPS30-DT in open-access papers:
MRPS30-DT is named in the same sentence as 13 diseases in open-access papers, as found by Europe PMC text mining. Sharing a sentence is not in itself a finding about the gene and the disease. The quoted sentences say what the papers report.
lung carcinoma (5 papers, 2022 to 2025). "Long non-coding RNA (lncRNA) MRPS30 divergent transcript (also known as BRCAT54) is recently reported to promote lung cancer." (PMID 35191803, 2022). "BRCAT54 (also known as MRPS30 divergent transcript) is an anti-tumor long non-coding RNA (lncRNA) in lung cancer, while its role in vestibular schwannoma (VS) is unclear." (PMID 35137654, 2022). "LncRNA MRPS30 divergent transcript (also known as BRCAT54) is recently reported to promote lung cancer." (PMID 35191803, 2022). "BRCAT54 (also known as MRPS30 divergent transcript) is an anti-tumor lncRNA in lung cancer." (PMID 35137654, 2022).
MRPS30-DT also shares sentences with these, for which no sentence is quoted: non-small cell lung carcinoma (5 papers); breast carcinoma (3); cancer (2); tumor (2); breast tumor (1); colon cancer (1); esophageal squamous cell carcinoma (1); gastric cancer (1); hemangioma (1); renal cell carcinoma (1); triple-negative breast carcinoma (1); Vestibular schwannoma (1).